EGFR (epidermal growth factor receptor)
Diseases named in the same sentence as EGFR in open-access papers (continued):
Sharing a sentence is not in itself a finding about the gene and the disease.
cancer (continued). "We therefore examined the total number of cancer-specific enhancer links in samples with and without KRAS or EGFR genetic alterations and in the highest quartile and remaining quartiles of expression of FOXM1 and MYBL2, respectively." (PMID 32925947, 2020). "Given that ERRFI1 functions a negative feedback inhibitor of EGFR signaling, we presumed that the function of the GC-ERRFI1 regulatory axis on different cancer hallmarks will be highlighted in this cell line." (PMID 32432675, 2020). "Although two growth factor receptors, EGFR and HER2, are amongst the best targets for cancer treatment, no agents targeting HER3, their kinase-defective family member, have so far been approved." (PMID 32847130, 2020). "Basal-type cancers with and without SCC features were characterized by abundant EGFR mRNA expression." (PMID 32978523, 2020). "Targeted therapies for oncogenic aberration in lung (e.g., EGFR and ALK kinase inhibitors) and breast (e.g., HER2 therapies) cancer have improved survival, but have not resulted in cures for all patients." (PMID 31137625, 2019). "A highly potent and non-specific anti-cancer drug, MMAE, was conjugated with peptide that mimics Cetuximab specificity for EGFR." (PMID 30700733, 2019). "While HTO did not modify the amount of EGFR in lipid raft membrane microdomains, it did enhance ERK signaling and dihydroceramide production, with a concomitant increase in cancer cell death." (PMID 31069012, 2019). "Immunostaining with anti-pan-CK and EGFR antibodies, with notable EGFR staining and the absence of α-SMA expression confirmed the carcinoma-like nature of NHRI-HN1." (PMID 31878324, 2019). "Samples with fusions involving oncogenes, such as EGFR, ERBB2, and RET, showed increased expression of those genes relative to samples without fusions across cancer types." (PMID 29617662, 2018). "In the present study, we focused on the strongly regulated novel gene by EGFR/ErbB2 blockade, PHLDA2 as it has not been investigated before as a target of oncogenic pathways in cancers." (PMID 29861842, 2018). "We revealed that the heme-stacking PGRMC1 dimer interacts with the EGF receptor (EGFR), which is involved in signal transduction during cancer proliferation, whereas the apo- or CO-bound PGRMC1 monomer does not bind to the EGFR." (PMID 30087538, 2018). "The shielded virus efficiently infected EGFR- and HER2-overexpressing cancer cells, demonstrating again that the shield does not sterically interfere with adapter-mediated receptor binding nor does it prevent virion uptake." (PMID 29386504, 2018). "In contrast, the EJ1 cell, which was the only cancer cell line in all 7 solid cancer cell lines we tested that was not reduced by 1 T SMF, showed a different EGFR pattern." (PMID 28061454, 2017). "Therefore, understanding the mechanisms that result in transient or nonpermanent amplifications of DHFR, EGFR, and alike in cancer will have a profound impact on how we view copy number control as well as how we identify novel biomarkers and therapeutic targets for treating drug-resistant cancers." (PMID 26755558, 2016). "Most clinical experiences suggest that the sEGFR is a circulating EGFR isoform with a protective role (negative biomarker) in NSCLC, representing a potential biomarker in this form of cancer early-detection." (PMID 27104520, 2016). "We used Western Blots to examine the EGFR expression and phosphorylation level and found that EGFR is highly expressed and phosphorylated in HCT116 and CNE-2Z cancer cells but not in CHO cells." (PMID 27223425, 2016).
cancer (continued). "The goal was to explore the specific roles of these receptors without any interference from EGFR and ERBB2 receptors as typically encountered in cancer-derived cell lines." (PMID 26745281, 2016). "Our hit list contains genes coding kinases with established oncogenic functions such as MET, EGFR, AKT, mTOR, RSK2 as well as genes that do not (yet) have an established role in cancer progression (NEK5, SIK2)." (PMID 27374095, 2016). "In this context, it is assumed that co-overexpression of EGFR, c-Src and NEU3 in cancers is not just coincident but probably an essential event in tumorigenesis." (PMID 25803810, 2015). "However, in the case of EGFR-mutant H1975 NSCLC cells (L858R and T790M positive), our study suggests that alternative EGFR signaling may be occurring mainly through the MAP Kinase and/or PI3K/Akt-stimulated mTOR pathway, resulting in cancer cell proliferation and survival." (PMID 26301867, 2015). "A link between PBK and EGFR has not been reported in GBM, although a functional relationship has been observed in other cancers." (PMID 26295306, 2015). "Comparing MFI of mature, differentiated keratinizing cancer cells to non-differentiated cancer area show enormous reduction in MFI, despite equal EGFR expression levels." (PMID 26120042, 2015). "In cancer cells with high MET activity, inhibition of EGFR activity alone likely is not sufficient to abrogate STAT3 activity." (PMID 24662938, 2014). "It implied that the regulation of miR-34a was not dependent on EGFR and ERK pathway after PAR2 activation in cancer cells." (PMID 23991105, 2013). "Here, we used two cancer stem-like cell lines, NCH644 and NCH421k, derived from patient GBMs without EGFR amplification, to define which growth factors are needed in the culture medium to maintain and expand GSCs." (PMID 24294177, 2013). "Although no gene showed a positive correlation with EGFR or MET expression, eight and nine such genes displayed a negative correlation with EGFR and MET expression, respectively, in cancer samples." (PMID 22211244, 2012). "The results in this study showed HER3 activation upon HER2Mab treatment in both MCF7 (low HER2) and MCF7-HER2 (high HER2) cancer cells independent of the HER3 ligand NRG1, and HER3 activation is a result of HER3/EGFR dimerization." (PMID 23342251, 2012). "Most slides from cancer-free tissue lacked expression of CCND1, CD44, CDH1, EGFR, ERBB2, KIT, keratins, NOTCH1, PAK1, PTGS2, SNAI1, and VIM but showed staining of MUC1, HIF1A, NKX2-1, SFTPC, and STAT3, which were also found in AdCa." (PMID 23028920, 2012). "In the study by Nielsen and al., immunohistochemical panel for basal-like cancers was defined as lack of ER and HER2 expression and positivity for CK5/6 or EGFR." (PMID 20426817, 2010). "Gold nanoparticles conjugated to anti-epidermal growth factor receptor (anti-EGFR) mAbs specifically and homogeneously bind to the surface of the cancer cells with 600% greater affinity than to the noncancerous cells." (PMID 21144040, 2010). "Additionally, clinical data in other cancer types has also indicated the existence of de novo and acquired resistance to gefitinib and interestingly, a clear link between EGFR levels and predicted response to EGFR-targeted agents including gefitinib has not been observed." (PMID 16819546, 2006). "However, it is not clear how many lncRNAs can be regulated by EGFR/MAPK signaling and, if any, what molecular cancer characteristics of these lncRNAs can contribute to EGFR/MAPK-mediated CRC promotion." (PMID 40190348, 2025).
cancer (continued). "Viability measurements of target cancer cells showed that BP-αCD3-αEGFR-ARC Exos can selectively induce cytotoxicity against EGFR-expressing BT-20 and MDA-MB-231 cells with EC50 in a range of 37–174 ng mL−1, but spare MDA-MB-453 cells lacking EGFR expression." (PMID 41419470, 2025). "While EGFR-TKIs are known substrates for major ABC drug transporters, the circumvention of ABC transporter-mediated drug resistance to EGFR-TKIs by Lingzhi/Yunzhi in experimental cancer models has not been reported." (PMID 40733125, 2025). "In light of this, our findings that RAF, MEK, PI3K and EGFR inhibitors did not cooperate with MLKL in killing CRC cells are not surprising since these agents promote, rather than inhibit, autophagy in various cancer cell types, including CRC cells." (PMID 39979285, 2025). "Results from these experiments determined that oxaliplatin‐loaded EVs conjugated with GE11 peptide showed significantly higher incorporation into EGFR‐expressing cancer cells compared to those without GE11 peptide conjugation, leading to increased apoptosis of cancer cells." (PMID 40385535, 2025). "Unlike EGFR and HER2 inhibitors that target receptor tyrosine kinases located on the cell surface, ALK, BRAF/MEK, and PI3K/AKT/mTOR inhibitors act on non-receptor kinases in intracellular signaling pathways critical for cancer cell proliferation and survival." (PMID 40872476, 2025). "UCK2 can non-metabolically activating EGFR-AKT signaling pathway to promote HCC progression and may provide novel UCK2-based therapeutic strategies for cancer treatment." (PMID 39179560, 2024). "Our current results may provide valuable insights that can be used to develop new cancer treatment strategies for NSCLC patients, including those who are first-generation EGFR-TKI resistant, without toxicity from direct treatment of AKT inhibitors." (PMID 35931945, 2022). "In addition, the continuous activation of Akt independent of EGFR is also an important reason for the emergence of resistance to CTX therapy; therefore, Akt inhibition is a strategy to sensitize cancer cells to CTX." (PMID 36387129, 2022). "The results of the driver gene detection for EGFR, ALK, and ROS1 in cancer cells from peripheral blood samples were negative (May 15, 2021)." (PMID 35029237, 2022). "Recent studies have reported that GL and its derivatives can bind to PGRMC1 (progesterone receptor membrane component 1), inhibit the interaction between PGRMC1 and EGFR (Epidermal growth factor receptor), then inhibit HCT116 and HuH7 cancer cell proliferation, while GA does not bind to PGRMC1." (PMID 36313350, 2022). "In this cancer cells, EGFR is activated without EGF stimulation when they are cultured in growth medium, perhaps due to high level of EGFR expression, and we have shown that TSP1‐CD148 interaction suppresses this EGFR activity." (PMID 34791835, 2022). "Although in numerous cancer cell systems, NTS signaling depends on EGFR activation, this is not the case in HT29 cells, since sSortilin/NTSR3 is unable to compete with EGF on the EGFR, and reciprocally, EGF is unable to compete with sSortilin/NTSR3 on its binding sites." (PMID 36233189, 2022). "Another bispecific antibody (hEGFRvIII-CD3) comprising two scFv fragments (one specific to the EGFRvIII antigen and another to the CD3 epitope) was designed to create a bridge between EGFR-expressing cancer cells and CD3+ T cells, and to prevent a non-specific targeting to EGFR-negative cells." (PMID 36185288, 2022). "Cancer cells with low expression of AREG and EREG may possibly indicated that it not sensitive to anti-EGFR therapies." (PMID 34884633, 2021). "Interestingly, SGS organoids showed collectively more proliferating progenitors, which expressed markers of cancer-related proliferative genes (e.g., CRABP2, EGFR) virtually absent, or low in controls." (PMID 34193871, 2021).
cancer (continued). "Moreover, STAT3 activation was independent of gp130/JAK activity or HER2/EGFR heterodimer formation and administration of PD173074 led to suppression of STAT3 activation and inhibition of cancer cell proliferation." (PMID 34830951, 2021). "The role of PRMB1 in cancer remains unclear, and while no direct links between PRMB1 and EGFR signaling have been established, it has previously been linked to p21 expression and cell cycle arrest in breast cancer." (PMID 34944063, 2021). "Indeed, on one hand we have an oncogene addiction toward EGFR pathway in ALL RAS wild type cells, but on the other hand we know that TS is essential for non-oncogenic pathways of cancer cells regardless of EGFR or RAS activation." (PMID 33613849, 2021). "As stated in our results, a similar distribution of EGFR immunostaining was observed between HPV and non-HPV-related cancers, so underrepresentation of p16-positive VSCC cases in our study may not be justified." (PMID 34944993, 2021). "Furthermore, upregulation of cancer cell proliferation was observed in accordance with the increase of the osmolarity of medium, and was then suppressed by CP380736, a specific EGFR inhibitor, and genistein, a nonspecific TKI." (PMID 32901097, 2021). "Overexpression of EGFR or HER2/neu is a strong predictor of a negative prognosis in a variety of malignancies and the development of monoclonal antibodies targeting such receptors has advanced cancer treatment." (PMID 35097027, 2021). "A similar distribution of EGFR immunostaining was observed between HPV and non-HPV-related cancers." (PMID 34944993, 2021). "In addition, our results indicate that short-term lysine deprivation would not significantly affect the survival of EGFR wild-type NSCLC and normal cells, which is consistent with reports from previous studies on normal cells and other types of cancers." (PMID 33450879, 2021). "Since Berberine and Costunolide do not directly target EGFR phosphorylation, DHW could be a supplementary medicine to tyrosine kinase inhibitors in cancer therapy." (PMID 32298294, 2020). "We therefore suggest that if EGFR is overexpressed, its activation can be increased by NEU3, but if EGFR is in a normal status, as in the normal intestinal mucosa, NEU3 activity is not able to transform EGFR into a cancer driver." (PMID 33233823, 2020). "The glycosylation of EGFR in HeLa cells is not affected by the levels of GOLPH3, and the consequence in other cancer cell lines is unknown." (PMID 33238647, 2020). "Using EGFR-expressing human adenocarcinoma MCF-7 cells, we demonstrated that in contrast to MNT with N-terminal epidermal growth factor (EGF), MNTN-affibody and MNT with EGF on the C-terminus did not stimulate cancer cell proliferation." (PMID 32194412, 2020). "However, they prolong patient survival only by several months and many patients with CRC, including those with cancer displaying dysregulated RAS signalling, do not respond to anti-EGFR therapies." (PMID 31091767, 2019). "Solely long-term application of Gefitinib (EGFR TKI) and Lapatinib (EGFR/Her2 TKI) induced an upregulation of PTPIP51/PTP1B interactions, thus, portraying a potential adaption mechanism of the cancer cell to the applied TKI treatment and not a direct effect of the TKI." (PMID 30360441, 2018). "Besides the known resistance mechanisms to EGFR TKIs, many NSCLC cancer patients exhibit innate resistance to TKIs without any known resistance mechanism." (PMID 29789542, 2018). "However, under pathological conditions, such as cancer, STAT proteins are constitutively phosphorylated by RTKs, including epidermal growth factor receptor (EGFR) and IGF1R, or non-RTKs, such as c-Src and JAK, thereby driving metastatic disease." (PMID 30013043, 2018). "Although these findings suggest that CEA may have anti-apoptotic effects in cancer cells, a direct relationship between high CEA levels and patient responses to EGFR-TKIs has not yet been established and requires additional research." (PMID 28705152, 2017).
cancer (continued). "Importantly, DDA-induced UPR is potentiated by overexpression of EGFR or HER2, providing a partial explanation as to how DDAs can effectively kill cancer cells without harming normal tissues." (PMID 28423644, 2017). "We studied whether or not CAT-SKL and EGFR SMKI erlotinib were acting on the same cells, or if each agent was targeting a distinct population of cells, i.e., the subset of cancer stem-like cells (CSCs) versus the bulk population of cancer cells." (PMID 28281569, 2017). "Given EGF would activate the PI3K/Akt/mTOR signaling pathway, it is crucial to investigate whether or not MeCDDA can alter the expression level of EGFR on SCLC cells or induce conformational changes in EGF protein structure, achieving its anti-cancer effect." (PMID 28671570, 2017). "We revealed that cell growth of most human solid cancer cell lines we tested, but not non-cancer cell lines, can be inhibited by 1 T SMF at higher cell densities, in which the EGFR-Akt-mTOR pathway may play essential roles." (PMID 28061454, 2017). "Thus, EGFR is a therapeutic target, not just against CRC, but also against other cancers in which it is abundantly expressed." (PMID 26569500, 2015). "Therefore, since the invasive capabilities of cancer cells were restored by MEK1, but not by myr-AKT, it was concluded that ERK is involved in the regulation of Snail through a VcanV2/EGFR signaling axis." (PMID 26515726, 2015). "In malignant tumors, constitutively activated HER2 and EGFR/HER1 not surprisingly stimulate many of the same intracellular signaling proteins and pathways as wild-type receptors, such as the MAPK, PI3K/AKT/mTOR pathway, Src kinase, and STAT transcription factors." (PMID 25674538, 2015). "The pretreatment RNA levels of Bim predicted the ability of EGFR, HER2 and PI3K inhibitors to induce apoptosis in EGFR-mutant, HER2-amplified and PIK3CA-mutant cancer cells, respectively, while Bim levels did not predict responsiveness to standard chemotherapies such as gemcitabine and cisplatin." (PMID 26405162, 2015). "Combination EGFR and MET inhibition with WZ4002 (a third-generation EGFR-TKI) and crizotinib demonstrated highly efficacious control in these cancer models, but neither of these drugs alone could induce a suppressive response." (PMID 25780909, 2015). "Indeed, current therapies for advanced CRC target molecules that are related to cancer progression [e.g. VEGF and EGFR], rather than counteract the initiation of metastasis." (PMID 23070965, 2012). "We speculate that the following occurs; 1) rapid growth of cancer cells results in overexpression of ROCK; 2) dysfunction of ROCK in cancer cells; 3) ROCK does not function in normal pancreatic cells, because they lack EGFR expression." (PMID 21722395, 2011). "In addition, no reports are available on the correlation pattern among EGFR, AKT, and Ki-67, a cancer cell proliferation index." (PMID 19662227, 2007). "The third group in our study, RCCs with totally negative EGFR staining, may include a group of cancers in which mechanisms other than EGF are responsible for cancer growth and progression." (PMID 14520458, 2003). "Netarsudil, fedratinib, and osimertinib—specific inhibitors of ROCK1, JAK and EGFR, respectively—are FDA-approved antiproliferative drugs with similar IC50 values in both HeLa and U2OS cells, whereas quercetin and pranlukast do not show any effect on cancer cells viability and proliferation." (PMID 41325773, 2025).